SATB2 (SATB homeobox 2)
Diseases named in the same sentence as SATB2 in open-access papers (continued):
Sharing a sentence is not in itself a finding about the gene and the disease.
microcephaly (1 paper, 2025). A congenital or acquired developmental disorder in which the circumference of the head is smaller than normal for the person's age and sex. "Thus Satb2−/− mice have a CP, a smaller lower jaw with an anterior defect, hypoplasia of the premaxilla and the nasocapsular region, and microcephaly." (PMID 40474278, 2025).
mucinous cystadenocarcinoma (1 paper, 2019). An invasive adenocarcinoma characterized by cystic changes and the presence of malignant glandular cells which contain intracytoplasmic mucin. "All malignant mucinous cystadenocarcinomas (7/7; 100%) expressed CK7, and were negative for PAX8 and SATB2." (PMID 31771640, 2019).
Neurodevelopmental delay (1 paper, 2023). "Importantly, dysfunction of these transcription factors in humans, as in SATB2-associated syndrome, is characterized by significant neurodevelopmental delays, limitations in speech, and severe intellectual disability." (PMID 37980357, 2023).
Obesity (1 paper, 2020). Accumulation of substantial excess body fat. "We found mHFD-induced obesity led to significant upregulation of Satb2 mRNA expression in the hypothalamus of mHFD female offspring in comparison to controls, but this did not occur in mHFD males." (PMID 32344561, 2020). "Using a mouse model of mHFD-induced obesity, we performed a qPCR screen to determine whether adverse maternal nutrition alters the expression of Satb2 mRNA in the developing VMN of GD17.5 offspring." (PMID 32344561, 2020).
olfactory neuroblastoma (1 paper, 2022). An olfactory neuroblastoma arising in the paranasal sinus. "This is the first study reporting the immunohistochemical expression profile of SATB2, GATA3, and CDX2 in olfactory neuroblastoma (ONB)." (PMID 35522392, 2022).
ovarian carcinoma (1 paper, 2024). A malignant neoplasm originating from the surface ovarian epithelium. "focal CK7 positivity with diffuse SATB2 positivity also reflects a primary gastrointestinal tumor, Conversely, diffuse CK7 expression with absent or negative SATB2 expression points to primary ovarian cancer, while diffuse positivity for both CK7 and SATB2 suggests a lower gastrointestinal origin." (PMID 39040449, 2024).
pancreatic NEN (1 paper, 2025). "Detailed characterization of pulmonary NEC, pulmonary carcinoid, pancreatic NEN, ileal NEN, and MiNEN was performed using immunohistochemical staining to detect pan-cytokeratin (panCK), Thyreoglobulin (TG), Calcitonin (CT) and the transcription factors CDX2, SATB2, TTF1, GATA3, ARX and PDX1." (PMID 41145514, 2025).
periampullary adenocarcinoma (1 paper, 2014). An adenocarcinoma that arises from the periampullary region. "Immunohistochemical expression of SATB1 and SATB2 was analysed in tissue microarrays with primary tumours and a subset of paired lymph node metastases from 175 patients operated with pancreaticoduodenectomy for periampullary adenocarcinoma." (PMID 25323550, 2014). "The prognostic value of SATB1 and SATB2 expression in periampullary adenocarcinoma has not yet been described." (PMID 25323550, 2014).
prostate (1 paper, 2024). "Overall, these studies will enhance our understanding of the role of SATB2 in prostate carcinogenesis." (PMID 38891096, 2024).
prostate adenocarcinoma (1 paper, 2024). "Expression of SATB2 protein was significantly higher in prostate adenocarcinoma tissues than in normal tissues." (PMID 38891096, 2024). "Using receiver operator characteristic analysis, SATB2 was a sensitive and specific marker for prostate adenocarcinoma (100.0%, 80.0%)." (PMID 38891096, 2024). "Since SATB2 protein is highly expressed in prostate adenocarcinoma tissues, patients are more likely to have an aggressive disease compared to those of a healthy person." (PMID 38891096, 2024). "The expression of SATB2 was significantly higher in prostate adenocarcinoma compared to normal tissues." (PMID 38891096, 2024).
Satb2-associated syndrome (1 paper, 2019). "In humans, the deletion or mutation of one allele within the Satb2 locus results in a disorder called Satb2-associated syndrome (SAS)." (PMID 30809123, 2019). "Satb2-associated syndrome (SAS) is a genetic disorder that results from the deletion or mutation of one allele within the Satb2 locus." (PMID 30809123, 2019).
steatosis (1 paper, 2022). Increased lipid within the cytoplasm of cells. "In the present study, SATB2 upregulates FASN, an enzyme responsible for lipogenesis, steatosis, NAFLD and HCC." (PMID 35152538, 2022).
tobacco use disorder (1 paper, 2026). "The other five loci contained promising coding and expression variants, including Trak2, a gene previously associated with CUD in human GWAS and Slc10a7, Plcl1, and Satb2 which have been associated with alcohol and tobacco use disorder." (PMID 42277005, 2026).
tooth agenesis (1 paper, 2021). A tooth disease characterized by failure to develop one or more missing teeth. "However, the roles of plenty of other odontogenic genes which have been reported to be associated with tooth agenesis such as SATB2, BMP4, GREMLIN2, LRP6 and the mechanism of decreased function of hDPSCs in patients with tooth agenesis is still not fully understood." (PMID 34863303, 2021). "However, the mechanism of how SATB2 mutation results in tooth agenesis in human is rarely studied." (PMID 34863303, 2021). "This novel SATB2 variant inhibited osteo/odontogenesis of hDPSCs through Wnt/β-catenin signaling pathway by regulating DKK1 and histone demethylase JHDM1D, thus leading to the phenotype of tooth agenesis in the SAS patient." (PMID 34863303, 2021).
tubular adenoma (1 paper, 2023). A usually polypoid neoplasm arising from the glandular epithelium. "Here, we assessed GS‐II binding and performed immunostaining for HIK1083 (specific to terminal αGlcNAc residues), MUC5AC, MUC6, and special AT‐rich sequence binding protein 2 (SATB2) in SSLs, MVHPs, and tubular adenomas (TAs)." (PMID 37036163, 2023).
ureteral tumors (1 paper, 2017). "Although highly sensitive, SATB2 is weakly positive in focal areas of some other tumors, such as pulmonary adenocarcinoma, pulmonary squamous carcinoma, bladder and ureteral tumors, and adenocarcinoma of the cervix, endometrium, and ovary." (PMID 28969003, 2017).
villous adenoma (1 paper, 2025). An epithelial neoplasm morphologically characterized by the presence of a villous architectural pattern. "Some of the cells were morphologically similar to intestinal villous adenoma, but they were negative by CK20, SATB2, and CDX-2, so ectopic or tumor metastasis in the digestive mucosa was excluded." (PMID 40013097, 2025).
tumor (124 papers, 2009 to 2026). "In both cohorts, lower CDX2 and SATB2 expression levels were associated with proximal tumor location, high tumor grade, MMR deficiency, and BRAF V600E mutation (p < 0.001 for all)." (PMID 39998677, 2025). "The primary aim of this study was to evaluate the associations between CDX2 and SATB2 expression and tumor-infiltrating immune cells in CRC." (PMID 39998677, 2025). "Although both expression groups were associated with one another (p < 0.001), there were many tumours with a discordant SATB2/CDX2 expression status (Kappa Cohens value: 0.30)." (PMID 34944797, 2021). "In breast cancer, the expression of SATB2 is significantly associated with increasing tumour grade and poorer survival." (PMID 32885593, 2020). "Since SATB2 is highly expressed in most tumours, it can be used as a diagnostic biomarker for cancer, and its targeted inhibition can be useful for the treatment and prevention of cancer." (PMID 32885593, 2020). "SATB1 expression was significantly associated with microsatellite stable tumours (p < 0.001), beta-catenin overexpression (p < 0.001) and SATB2 expression (p < 0.001)." (PMID 22935204, 2012). "In contrast to SATB1, tumours classified as having higher transcript levels of SATB2 were significantly associated with a poorer OS." (PMID 19642980, 2009). "SATB2 mRNA expression is significantly associated with increasing tumour grade and poorer overall survival." (PMID 19642980, 2009). "When applying these markers in the diagnostics of tumors of uncertain origin, it needs to be noted that loss of CDX2 and SATB2 expression was associated with higher tumor grade, proximal tumor location, BRAF mutation, and dMMR, which also corresponds with the findings of the previous studies." (PMID 39998677, 2025). "Moreover, SATB2 immunoreactivity was associated with patients’ sex, tumor localization, and grade of differentiation." (PMID 40076993, 2025). "In addition to a high CpG island methylator phenotype, factors such as high microsatellite instability, BRAF/RNF43 mutations, consensus molecular subtypes, and high tumor mutational burden are also correlated with decreased mRNA expression of SATB2." (PMID 40636538, 2025). "SATB2 can be useful in histologic samples with low bone production to identify cells with osteoblast differentiation and distinguish neoplastic bone caused by tumor mesenchymal cells from periosteal bone reaction." (PMID 39371880, 2024). "The results showed that Cdh1, Fas, and Satb2 were strongly associated with neoplasms, whereas Fas was related to immune system diseases and nervous system diseases, hinting that they might have a stronger correlation with CIPN." (PMID 37623249, 2023). "Recent studies demonstrated that SATB2 is associated with tumor growth or suppression." (PMID 33124191, 2020). "Furthermore, SATB1′s expression was found to be associated with microsatellite stable tumours and correlated with beta-catenin’s and SATB2′s levels." (PMID 31450715, 2019). "Although a significant association was found between SATB2 expression and poor prognosis, the small number of positive cases makes it hazardous to draw any conclusions on the potential prognostic value of SATB2 expression in PB-type tumours." (PMID 25323550, 2014). "Immunohistochemical analysis of 1882 tumours from nine independent CRC cohorts revealed that SATB2 was expressed in 85% of all tumours, suggesting the utility of SATB2 as a diagnostic marker for CRC, particularly when used in combination with cytokeratin 20 (CK20)." (PMID 22333599, 2012). "SATB2 mRNA expression is significantly associated with increasing tumour grade and poorer OS." (PMID 19642980, 2009). "The associations of SATB2 expression with patient gender and tumor location demonstrated in the present study, as well as the numerous discrepancies in the results of previous studies, indicate the complexity of the regulation of SATB2 expression in the colon and CRC tissues." (PMID 40076993, 2025).
tumor (continued). "In vivo, SATB2 overexpression inhibited xenograft tumor growth and lung metastasis, while LCN2 overexpression rescued these suppressive effects." (PMID 41736683, 2026). "Here, we demonstrate that SATB2 exerts tumor-suppressive effects by impairing NSCLC cell proliferation, migration, invasion, and EMT." (PMID 41736683, 2026). "Our findings uncover a novel epigenetic-metabolic crosstalk pathway in NSCLC, providing new insights into the molecular mechanisms of SATB2-mediated tumor suppression and potential therapeutic targets for NSCLC." (PMID 41736683, 2026). "The special AT-rich sequence-binding protein 2 (SATB2) is a well-established tumor suppressor in NSCLC, but its downstream epigenetic and metabolic regulatory mechanisms remain largely unclear." (PMID 41736683, 2026). "SATB2 was likewise strongly and diffusely positive in tumor nuclei, a highly specific feature of colorectal lineage and rarely seen in pulmonary adenocarcinoma." (PMID 41310725, 2025). "Subsequent measurement of the weight and volume of tumor tissue confirmed that radiotherapy after SATB2 silencing significantly inhibited tumor growth." (PMID 40078194, 2025). "Previously, only a few studies have examined the associations between tumor-infiltrating immune cells and the expression of CDX2 or SATB2 in CRC." (PMID 39998677, 2025). "Evaluate expression and localization of SATB1 and SATB2 across paired human colon/rectum and tumor samples." (PMID 40177244, 2025). "The mRNA expression level of SATB2 in tumor tissues from both COAD and READ patients was significantly lower than that in adjacent normal tissues, consistent with the results of previous studies." (PMID 40636538, 2025). "The results of both bioinformatics and experimental analyses demonstrated that SATB2 expression was downregulated in CRC tumor tissues and that SATB2 hypermethylation was detected in various regions, including the promoter." (PMID 40636538, 2025). "Concurrently, the TUNEL assay revealed a significant increase in the apoptosis rate within tumor tissues following SATB2 silencing and radiotherapy (the Sh-SATB2+IR group)." (PMID 40078194, 2025). "Nevertheless, the methylation status of the SATB2 promoter was significantly correlated with tumor differentiation (p = 0.04) and lymphatic metastasis (p = 0.02) in CRC patients." (PMID 40636538, 2025). "In our series, consistent with a bone-forming tumor, cells adjacent to woven bone—as well as those distanced from it—revealed SATB2 positivity." (PMID 40075784, 2025). "Here, we further demonstrated that statins effectively reverse the expression patterns of SATB1 and SATB2 in both 2D cell cultures and 3D spheroid model systems, leading to a reduction in tumor burden in in vivo experiments." (PMID 40689929, 2025). "We further analyzed the correlations between CDX2/SATB2 expression and immune cell densities separately at the tumor center and at the invasive margin, and the findings were largely similar to those for overall immune cell densities." (PMID 39998677, 2025). "Correlation of expression of SATB1 and SATB2 across different grades and stages of tumor samples towards understanding CRC progression." (PMID 40177244, 2025). "Then, MSP was performed to examine the methylation pattern of SATB2 in the promoter region in both CRC tumor and adjacent normal tissues." (PMID 40636538, 2025). "The conclusive identification of PHO is aided by the presence of SATB2 protein within tumor tissues." (PMID 41479782, 2025). "More importantly, we found that in the tumor tissues, the inhibition of the Wnt/β-catenin signaling pathway was the most obvious following SATB2 silencing and radiotherapy (the Sh-SATB2+IR group)." (PMID 40078194, 2025). "Current immunohistochemical (IHC) and molecular analyses, including RUNX2, KPNA2, and SATB2 as biomarkers, support the osteogenic origin of the tumor and assist in differentiating OS from morphologically similar neoplasms." (PMID 40862758, 2025).
tumor (continued). "The downregulated expression of SATB2 in CRC tumor tissues was significantly correlated with SATB2 hypermethylation, and the mRNA expression level of SATB2 significantly increased following AZA treatment in certain CRC cell lines." (PMID 40636538, 2025). "While many reports suggest that SATB2 exerts a tumor suppressive effect, few studies propose that SATB2 upregulation contributes to tumor progression." (PMID 40689929, 2025). "Downregulation of Wnt/β-catenin signaling and subsequent modulation of chromatin organizers SATB1 (oncogenic) and SATB2 (tumor suppressor), leading to reversal of epithelial-mesenchymal transition (EMT)." (PMID 41170235, 2025). "Inhibition of SATB2 has been shown to lower tumor proliferation and increase sensitivity to chemotherapy." (PMID 39769005, 2024). "SATB2, a transcription factor involved in gene regulation, has potential molecular mechanisms related to cell differentiation, cell migration, and tumor metastasis, suggesting its significance as a biomarker." (PMID 37719843, 2023). "KI-67, RUNX2 and SATB2 expression differed depending on the benign or malignant course of the tumor under denosumab therapy." (PMID 37686526, 2023). "The analysis identified the combination of CK7/CK20/SATB2 to be the smallest panel with the highest sensitivity (85.1%) and specificity (100%) for predicting tumour origin with an ROC AUC of 0.965 (p < 0.001; SE: 0.018, 0.930–1.000 95% CI)." (PMID 35027072, 2022). "MCTS of SAOS2 and MHM show areas suggestive of extracellular matrix deposition and tumour cells were focally positive for SATB2, a marker for osteogenic differentiation." (PMID 34921235, 2022). "SATB2-AS1 is a colorectal-specific lncRNA expressed in colorectal tissues and CRC cells that inhibits tumor metastasis and regulates the immune response by activating SATB-2 in CRC." (PMID 36230757, 2022). "Loss of SATB2 was associated with CK7 expression, advanced tumor stage, mucinous or signet ring cell morphology, high grade, right-sided localization but was borderline insignificant relative to PD-L1 expression." (PMID 36351995, 2022). "The homeobox gene SATB2 was shown to be a direct target of miR-31 in CAFs and is involved in promoting tumor cell migration and invasion." (PMID 36313626, 2022). "Our results expand the spectrum of SATB2 and GATA3-positive neoplasms, with relevant practical diagnostic correlates, and suggest that Hyams’ grade 4 ONBs are not only clinically but also biologically different from lower grade ONBs." (PMID 35522392, 2022). "Our data functionally validate SATB2 as a driver of enhanced tumor propagation and drug resistance in vivo." (PMID 33527896, 2021). "MCR:SATB2 transgenic animals, in addition to developing tumors faster, had a high prevalence of tumor burden in internal organs, which is uncommon in MCR:EGFP controls, even in animals with very large tumors." (PMID 33527896, 2021). "Significant differentially regulated genes from SKMEL2 iSATB2 were compared with zebrafish primary tumor RNA-seq (MCR:SATB2 vs. MCR:EGFP) using both Gene Set Enrichment Analysis (GSEA) and Ingenuity Pathway Analysis (IPA)." (PMID 33527896, 2021). "In different tissues and tumor types, SATB2 has been shown to play a role in oncogenic transformation and proliferation, or epithelial-to-mesenchymal transition (EMT), migration, and self-renewal." (PMID 33527896, 2021). "Exosomal miR-31-5p was found to be remarkably upregulated in HExo, and promotes tumor progression by targeting Special AT-Rich Sequence-Binding Protein 2 (SATB2) and activating MEK/ERK pathway." (PMID 34074322, 2021). "SATB2 donors have a significantly higher estimated fraction of tumor propagating cells (median estimate 1/21.6 cells for MCR:SATB2 vs. 1/10,879 cells for MCR:EGFP, Mann Whitney p=0.0159*)." (PMID 33527896, 2021). "In vivo bioluminescent imaging of orthotopic tumors showed that silencing SATB2 dramatically inhibited GSC‐driven tumor growth in mouse brains." (PMID 33124191, 2020).